HLA-DRB1 (major histocompatibility complex, class II, DR beta 1)
Diseases named in the same sentence as HLA-DRB1 in open-access papers (continued):
Sharing a sentence is not in itself a finding about the gene and the disease.
tumor (continued). "Among the 5,291 coding somatic mutations found in an aggregate of 240 matched tumour/normal samples, we found 26 overlapping variants in SH-SY5Y inside 24 genes among which 9 were rare amino-acid changing mutations inside 7 genes (ALK, FOXD4L1, HLA-DRB1, NBPF10, NBPF14, PABPC3, TEKT4)." (PMID 25528190, 2014). "Here, the tumor cells elevate expression of immune signaling MHC II molecules (CD74, HLA-DRB1, HLA-DPA1) and immune-regulating secretory proteins (REG4, AGR2, AGR3), with AGR2 and REG4 specifically upregulated in RCRC." (PMID 41450739, 2025). "Specifically, we discovered that fucosylation of tumor-expressed MHC-II protein HLA-DRB1 triggers CD4+T cell-mediated induction of tumor-infiltrating immune cells and tumor suppression." (PMID 38646527, 2024). "RNA was extracted from tumor tissue, and the expression of DEIRGs including GREM2, CTSS, TINAGL1, ACKR1, HLA-DRB1, and STC2 was verified using real-time quantitative reverse transcription PCR (RT-qPCR)." (PMID 39735532, 2024). "Fucosylation of the major histocompatibility complex-II HLA-DRB1 enhances CD4+ T cell immunity and enhances anti-PD-1 efficacy in a murine tumor model." (PMID 37388743, 2023). "Cluster Fib_5 prominently expressed MHC-II genes (HLA-DQA1, HLA-DQA2, HLA-DQB1, HLA-DRB5, HLA-DRB1, HLA-DRA, HLA-DPA1, and HLA-DPB1), indicating their role as antigen-presenting cells with tumor-suppressing effects." (PMID 37533434, 2023). "Multiple genes (HLA-DRA, HLA-DRB1, OAS1, and CD74) differentially expressed in NSCLC B cells, peripheral blood lymphocytes, and tumor T cells had concordant prognostic indications at the mRNA and protein expression levels." (PMID 35804895, 2022). "This was further supported by the high levels of MHC I/II molecules (HLA–B, HLA-C, HLA-DRB1 and HLA-DQA1) expressed in cDC-CD1C-AREG from low tumor infiltration group as well as inflammatory cytokines and chemokines (IL1B, VEGF and CCL4, etc.)." (PMID 36532059, 2022). "Among the identified DE genes in NSCLC PBL T cells and tumor T cell clusters, HLA-DRA, HLA-DRB1, OAS1, and CD74 had concordant prognostic indications at the mRNA and protein expression levels in bulk NSCLC tumors with resectable disease." (PMID 35804895, 2022). "Four genes belong to the HLA family: HLA-DQA1, HLA-DRB1, HLA-DQB1, and HLA-F, which were significantly overexpressed in RCC tumor tissues compared with paired adjacent normal tissues." (PMID 25784652, 2015). "In addition, all urinary proteins, except for four (TMEM132A, HLA-DRB1, SLC10A3, RNF150), have been reported as candidate biomarkers for thirty-five neoplastic diseases." (PMID 36918772, 2023). "We also noticed that MHCII molecule including HLA-DPA1, HLA-DRB1, HLA-DQA1 and CD74 were significantly downregulated in this cluster of macrophages, which may contribute to sub-optimal tumor antigen presentation." (PMID 37957625, 2023). "In concurrence with NanoString analysis of our own tumor samples, these included IFN-γ signaling genes STAT1, CXCL10, and IDO1; antigen presentation molecules HLA-DQA1 and HLA-DRB1; important T cell molecules GZMB and IL7R; and B cell–related molecules CD79A and CXCL13." (PMID 35132960, 2022). "However, Mono-FCGR3A in high tumor infiltration group expressed lower levels of MHC molecules, inflammatory cytokines and chemokines (HLA-DRB1/HLA-DPB1, TNF, IL1B, CCL3 and CCL4), which meant the sub-cluster was less involved in immune responses." (PMID 36532059, 2022). "In addition, we observed that several MHC family members, such as HLA-DRA, HLA-DRB1, HLA-DPA1 and HLA-DPB1, were highly expressed in response tumour samples." (PMID 36581917, 2022). "This suggests that HLA-DRB1*07 carriers are likely to present tumour cell derived antigenic peptides, and that downregulation of HLA expression in HRS cells is required to overcome CD4+ T cell orchestrated anti-tumour responses." (PMID 34830986, 2021).
tumor (continued). "None of the HLA-DRB1 and -DQB1 alleles showed a specific tendency for histological type or clinical stage of the tumours." (PMID 9374382, 1997). "Similarly, in a second tumor model, only T cells transduced with the PIK3CAE545K-specific TCR, suppressed (p = 0.004) the growth of the cell line CCL-225, which also naturally expressed the E545K mutant protein, following transduction with HLA-DRB1*04:01." (PMID 41410746, 2025). "It is worth noting that the interaction between HLA‐II molecules (such as HLA‐DRA, HLA‐DRB1, HLA‐DRB5, HLA‐DQB1, HLA‐DPB1, HLA‐DPA1, HLA‐DMB and HLA‐DMA) and the receptor CD4 was exclusively detected in the cell communication between malignant cells from single‐primary tumours and Tregs." (PMID 39601163, 2024). "The consistent trends that we observed in higher tumor fucosylation and fucosylated HLA-DRB1 across anti-PD1 responders versus non-responders between the three independent cancer center cohorts support their potential utility as biomarkers of anti-PD1 responsiveness." (PMID 36690875, 2023). "Both HLA-DRA and HLA-DRB1 were underexpressed in NSCLC PBL T cells and overexpressed in NSCLC tumor C11 /C6-LAYN CD8 T cell clusters, C14 CD4/CD8 T-cell clusters, and suppressive tumor Tregs of CD4-C9-CTLA4 cells vs. other tumor-infiltrating Tregs of CD4-C8-FOXP3 cells." (PMID 35804895, 2022). "Moreover, we observed a reduced expression of HLA class II molecules (CD74, HLA-DRA, HLA-DRB1, HLA-DMA), which might affect the number and function of CD4+ T lymphocytes in the tumor microenvironment." (PMID 36153593, 2022). "Notably, HLA-II expression in tumor cells was not uniform across the genes examined, with significantly higher HLA-DRB1 than HLA-DQA1, HLA-DQB1, and HLA-DPB1 (p < 0.0001, Kruskal–Wallis)." (PMID 35831288, 2022). "However, analysis of single‐cell RNA‐sequencing (RNA‐seq) of GB patient tumors revealed that tumor cells do not express CIITA nor genes encoding for MHC‐II antigen processing (CD74, HLA‐DMA, HLA‐DOA) and presentation (HLA‐DQA1, HLA‐DQB1, HLA‐DRA, HLA‐DRB1, HLA‐DRB5)." (PMID 39535369, 2025). "Hence, the amount of T cells CD8, T cells CD4 memory activated, NK cells activated were positively relevant to the expression level of HLA-DRB1, suggesting that HLA-DRB1 expression may be closely related to the maintenance of anti-tumor immune activity of the TME." (PMID 36129956, 2022). "Other proteins, including HLA-A, HLA-DMA, HLA-DQA1, HLA-DQB1, HLA-DRA, HLA-DRB1, and HLA-DRB5, were not reported on tumor–host immunological interactions, which indicated the proteins need further studies to testify them as novel OC biomarkers for tumor immunology." (PMID 31258820, 2019).
infection (60 papers, 2008 to 2025). The state of being infected such as from the introduction of a foreign agent such as serum, vaccine, antigenic substance or organism. "It is postulated that infection with SARS-CoV-2 or another virus triggers an uncontrolled immune response in genetically predisposed individuals (HLA-DRB1), with excessive release of proinflammatory cytokines and cellular activation." (PMID 39044822, 2024). "Concerning the HLA-II alleles that are part of the haplotype, it has been published that the HLA-DRB1*13 allele is associated with a risk of infection." (PMID 39125781, 2024). "Both, PD and RA share the same risk factors, including HLA-DRB1-04 as a genetic factor, smoking and infection with EBV and cytomegalovirus." (PMID 36091038, 2022). "A recent study reported that a variety of HLA-DRB1 alleles/haplotypes were associated with altered Ct infection risk, and differential rate of clearance in a cohort of Columbian women; HLA-DPB1 alleles were not examined." (PMID 36248887, 2022). "We next sought to model these closely related (yet discordant with respect to their association with infection) pairs of HLA-DRB1 alleles binding to CMV peptides to understand how their amino acid differences impact the electrostatic potential in the peptide-binding groove." (PMID 40049169, 2025). "We observed that HLA-DRB1*15 was significantly associated with symptomatic infection, and HLA-DRB1*13 and 15 were associated with mild to severe degrees of COVID-19 disease, which suggests both alleles may link with a robust immune response and seroconversion." (PMID 36366349, 2022). "Combined with the previous hypothesis, we speculate that for a subset of children with the class II HLA allele HLA-DRB1*04:01, previous infection with SARS-CoV-2 leads to superantigen-mediated immune activation." (PMID 36438816, 2022). "However, some HLA‐DRB1 alleles are associated with enhanced or muted post natural infection and vaccination T‐cell responses." (PMID 35156709, 2022). "Sri Lankans with HLA-A*31 and HLA-DRB1*08 might be more susceptible to DSS, during the secondary infection, and people with HLA-A*24 and HLA-DRB1*12 were more likely to have DHF during the primary dengue infection." (PMID 30759739, 2019). "In addition, the HLA-DRB1*0701 polymorphism was identified as a novel genetic risk factor for the development of GBS with preceding infection." (PMID 26204120, 2015). "In fact, the disease in childhood is at an early stage, and either a longer time of infection or more than one risk factor may be necessary to develop the disease, such as the presence of the HLA-DRB1*0301 allele observed in the study of Larizza and colleagues." (PMID 35799701, 2022). "The statistical analysis of mortality rates in carriers and non‐carriers indicates that individuals with HLA‐A*23 and HLA‐DRB1*10 have significantly higher fatality rates after infection with COVID‐19." (PMID 40366340, 2025). "After infection for 24 h and 48 h, the cell viability of HUVECs with hsa-HLA-DRB1 overexpression was significantly lower than that of the control." (PMID 40419622, 2025). "In contrast, Class1 was dominated by viral-infection annotations and antigen presentation (e.g., HLA-DRB1/DQB1/C, CD74, CTLA4, GZMB, PRF1), consistent with HIV-associated immune activation." (PMID 41394852, 2025). "This study identified the multiple pathways of HLA-DRB1, which were related to immunity, cell apoptosis and growth, and pathogen infection." (PMID 37569411, 2023). "HLA-DRB1 * 04 and HLA-DRB1 * 08 genotypes seem to increase the risk for infection, whereas HLA-DRB1 * 03 and HLA-DRB1 * 07 genotypes seem to decrease the risk." (PMID 37110254, 2023). "It was also found that HLA-DRB1 homozygous women had a LP effect on clearance and an EO effect related to persistence events, suggesting that this characteristic could represent a genetic disadvantage for its carriers as it makes them more susceptible to Ct infection." (PMID 34145318, 2021).
infection (continued). "Specific associations with HPV type were found for most HLA-DRB1 and DQB1 alleles and haplotypes identified in the study population, highlighting differences in the relationship with the clinical course of such infection in a host." (PMID 32350356, 2020). "Due to its biological function in the immune response, polymorphisms in genes of the HLA class II molecules (HLA-DRB1 and HLA-DQB1) are relevant candidates for studying their possible influence on the outcome of infection." (PMID 25938667, 2015). "In HLA class II, the HLA-DRB1*0901 frequency was significantly decreased in secondary infection of DSS in VL 04-05 (OR = 0.35, P = 0.0025, Pc = 0.03)." (PMID 18827882, 2008). "A pathogen-influenced signaling pathway was also found in this study, which implied that HLA-DRB1 might participate in signaling pathways relevant to pathogen infection." (PMID 37569411, 2023). "HLA-DPA1*01:03/DPB1*02:01 [for FAAGLFLRKLTSKEL from DENV serotype 2 and HLA-DRB1*11:01 for the other 2 peptides from serotype 3] could suffer from a relatively higher predilection for DHF following infection with DENV serotypes 2 and 3, respectively." (PMID 29692780, 2018). "HLA-DRB1*11 and 14 may be associated with viral clearance in the cases of HBV subgenotype C2 infection." (PMID 29914514, 2018). "Meanwhile, HLA-DRB1 alleles that identified in control group and not case patients were also important as a predictive genetic marker against infection with this parasite." (PMID 30416723, 2018). "Moreover, the frequency of HLA-DRB1*0901 in particular was significantly decreased in DSS when compared with DHF in DEN-2 infection (P = 0.02)." (PMID 18827882, 2008). "In conclusion, these results suggest that HLA‐DRB1 and ‐DQB1 polymorphism might be associated with different levels of IgG against HPV16 infection, but IgM production and the type of infection (transient or persistent) seem to occur independently of these variants." (PMID 40600436, 2025). "Similarly, another recent paper describing an association of HLA-DRB1 alleles with asymptomatic infection did not genotype for HLA-B32." (PMID 37468623, 2023). "Therefore, the HLA-DRB1*11 allele would not provide protection against infection but rather against the development of symptoms within our study population." (PMID 37845715, 2023). "Likewise, another recent paper describing an association of HLA-DRB1 alleles with asymptomatic infection did not genotype for HLA-B." (PMID 34031661, 2022). "To directly test this assumption and define the role of OC43-elicited T cells that are cross-reactive with SARS-CoV-2, we develop a model of sequential infections with OC43 followed by SARS-CoV-2 in HLA-B*0702 and HLA-DRB1*0101 Ifnar1−/− transgenic mice." (PMID 38278784, 2024). "One-fifth of upregulated DEPs in the AD retinas were related to immune responses, including HLA-DRB1, APOC1, S100A1, HLA-E, IBA1, and S100β, and involved lymphocyte and myelomonocyte activation in the presence of neuroinflammation and infection." (PMID 36773106, 2023). "Immune-suppressive phenotypes were also detected in cDCs during infection, with notable downregulation of HLA-DR genes HLA-DRA and HLA-DRB1 along with multiple paralogues (HLA-DPA1/B1 and HLA-DQA1/B1) in cDCs but not cytokine/chemokine genes." (PMID 37968278, 2023). "The majority of the genes in this cluster were related to the immune response to infection including OAS-1/3, IFI44L, HLA-A and HLA-DRB-1/4." (PMID 34593881, 2021). "HLA-DRB1*04 is classified as MHC class II, which presents antigens to CD4+ T cells at the site of infection." (PMID 34963463, 2021). "Thus, nAIGAs are rare (1.4%) even among patients with unexplained, severe disease due to mycobacteria, including HLA-DRB1*15:02 or 16:02 patients, and are therefore unlikely to be driven by the infection." (PMID 38470480, 2024).
infection (continued). "In general, infected HLA‐DRB1*15:02 HCW in this cohort tended to cluster at the lower end of T‐cell responsiveness to both spike and nucleoprotein, often making little or no T‐cell response after infection." (PMID 35156709, 2022).
cancer (51 papers, 2009 to 2025). A tumor composed of atypical neoplastic, often pleomorphic cells that invade other tissues. "Some examples include the association of a specific allele with the occurrence of cancer, the association of HLA-DRB1 heterozygosity with better outcomes in viral infections, and the association of HLA class I homozygosity with checkpoint inhibitor inefficacy in cancer therapies." (PMID 35349604, 2022). "According to a large-scale genetic analysis, idiopathic RPF is associated with HLA-DRB1*03 and neoantigens generated by cancer may cross-reactive with autoantigen in RPF patients having HLA-DRB1*03." (PMID 34565447, 2021). "Indeed, several studies performed in Africa, Asia, and Latin America have shown different susceptibilities to HPV and risks of HPV-induced cancers dependent on the ethnic origin and the expression of HLA-DRB1/DQB1 alleles." (PMID 31483832, 2019). "Consequently, the HLA-DRB1 71-Glu variant may implicate a more effective control of preventing an HPV16 infection that ultimately protects against HPV-driven cancers." (PMID 34642315, 2021). "Volcano plot analysis highlighted that HLA‐DRA and HLA‐DRB1 were significantly upregulated in high HLA‐DR cancer cells, particularly in HBV samples." (PMID 40464412, 2025). "We noticed that some MHC class II genes (HLA-DMA, HLA-DPA1, HLA-DPB1, HLA-DRA, HLA-DRB1) were significantly down-regulated in cancer cells with relatively poor differentiation states compared with those with better differentiation states for 5/6 mGC patients." (PMID 37347037, 2023). "In the same study, they found an association between HLA-DRB1*03, HLA-DRB1*13, and protection against this cancer, while HLA-DRB1*04 was linked to a poor prognosis in their study population." (PMID 34712820, 2021). "The somatic mutations of the organoids were identified and cancer genes in the most relevant BC genes were also found, including ERBB4, HLA-DRB1, PDE4DIP, PTPN22." (PMID 32774159, 2020). "The carcinoma (encircled in red) surrounding normal appearing tonsillar tissues (encircled in yellow) exhibited appreciable amount of HLA-DRB1 expression." (PMID 28383029, 2017). "Several proteins involved in cancer pathways had mutations in more than one patient, the most common being MUC4, GOLGA6L2, DSPP, FOXO6 and HLA-DRB1." (PMID 25605237, 2015). "Our analysis also identified several antigen-presenting molecules as potential cancer drivers, including one class I (HLA-C), one class II (HLA-DRB1), and three HLA-like proteins (CD1C, CD1E and MR1)." (PMID 26485003, 2015). "Here, we conducted a large-scale pancancer association analysis of HLA-A, -B, and -C (class I) and HLA-DRB1, DQA1, DQB1, DPA1, and DPB1 (class II) genes to address whether specific HLA alleles contribute to cancer risk." (PMID 37558689, 2023). "HLA class II molecules like HLA-DPB1, HLA-DRA, HLA-DRB1, and HLA-DQB1 are associated with antigen processing and presentation to CD4+ T cells, and the down-regulation of these genes is related to poor prognosis of cancers." (PMID 36417424, 2022). "HLA-DRB1 plays a crucial role in humoral and cellular immunology, and impaired HLA-DRB1 expression was linked to the development of several diseases, including cancer." (PMID 34072580, 2021). "The main pathways of methylome biomarkers were associated with calcium signalling (CACNA1E, RYR2, RYR3), cancer pathways (DCC, RASSF1, WNT1, CTNNA2), multiple neurodegenerative diseases (WNT1, DNAI1, RYR2, RYR3), immune system disorders and cell adhesion (HLA-DRA, HLA-DRB1, HLA-DRB5)." (PMID 40524349, 2025). "To quantify this finding, we developed an HLA‐DR score based on all upregulated HLA‐DR genes (HLA‐DRA, HLA‐DRB1, and HLA‐DRB5) and found that HBV cancer cells exhibited significantly higher HLA‐DR scores than NBNC cancer cells." (PMID 40464412, 2025).